ICAM1 (intercellular adhesion molecule 1)
Diseases named in the same sentence as ICAM1 in open-access papers (continued):
Sharing a sentence is not in itself a finding about the gene and the disease.
tumor (continued). "Accordingly, in a previous report, CRT has shown to promote tumor lymphocyte infiltration and enhance the efficacy of immunotherapy, ascribing such effect to the upregulation of adhesion molecules such as ICAM-1 and VCAM1 in tumor endothelium." (PMID 33584695, 2020). "The expression of ICAM-1 on circulating tumour cells promotes their extravasation through an interaction of this adhesion molecule with β2-integrins on arrested neutrophils." (PMID 32806712, 2020). "A recent paper by van Hooren and colleagues demonstrated the up-regulation of ICAM-1 expression on tumor ECs treated with Sunitinib and an agonistic anti-CD40 monoclonal antibody." (PMID 32352958, 2020). "[111In]In-anti-ICAM-1 uptake in tumours at 72 h post injection was approximately 3-fold higher than non-specific isotype-matched [111In]In-mIgG2a control (19.3 ± 2.5%ID/g versus 6.3 ± 2.2%ID/g, P = 0.0002)." (PMID 32135474, 2020). "Surprisingly, however, we only observed an increased uptake of [111In]In-anti-ICAM-1 in the irradiated tumour on one out of three mice in that group in our in vivo study." (PMID 32135474, 2020). "IL6 trans-signaling enhances both E- and P-selectin interactions and ICAM1 dependent T-cell transmigration on tumor vessels." (PMID 33381115, 2020). "Zinc can also diminish the expression of intercellular adhesion molecule-1 (ICAM1) to suppress tumor cell invasion and adhesion." (PMID 32340289, 2020). "Representative sections of xenograft tumours were processed for autoradiography that confirmed heterogeneous uptake of [111In]In-anti-ICAM-1 in PSN-1 tumours." (PMID 32135474, 2020). "STING activation leads to CD8+ T cell tumor infiltration and has also been shown to enhance the upregulation of adhesion molecules (e.g., ICAM1 and VCAM1) on ECs, alterations that altogether promote anti-cancer immune responses." (PMID 32974337, 2020). "It has been proved that soluble ICAM-1 (sICAM-1) facilitates the growth of tumor cell and allows the tumor cell to bypass immune recognition through combining circulating lymphocytes." (PMID 32802118, 2020). "The initial clustering of tumor cells and neutrophils is dependent on both physical trapping and adhesive interactions between neutrophils and endothelial ICAM-1." (PMID 33101283, 2020). "MMPs can also shed intercellular-adhesion molecule 1 (ICAM-1) from the tumor cell surface, a protein that is important for the adhesion of cytotoxic T lymphocytes and NK cells to target cells." (PMID 32063906, 2020). "ICAM1‐Gd or IgG‐Gd was i.v. administered into ICAM1‐expressing PANC‐1 tumor‐bearing mice at a dosage of 5 mg kg−1 mouse weight." (PMID 33344137, 2020). "Initial report on the participation of tumor endothelium in leukocyte infiltration reported a role for ICAM-1." (PMID 32014047, 2020). "Low expression of E‐selectin, intercellular adhesion molecule (ICAM) 1/2 and vascular adhesion molecule 1 (VCAM1) in tumour‐associated ECs results in the loss of tight connections in the tumour vascular endothelium." (PMID 32588948, 2020). "Considering molecular mechanism, correlation between ICAM-1 expression, cellular aggregation and rituximab anti-tumor activity was determined by flow cytometry, aggregation assay, CMC and ADCC assays as well as MTT assay." (PMID 33288735, 2020). "Most importantly, in the TNBC mouse model, ICAM1-specific CAR-T cells significantly reduced the growth of the TNBC tumor, resulting in long-term remission and improved survival." (PMID 33072116, 2020). "ICAM-1 can suppress tumor metastasis by inhibiting M2 macrophage polarization through blockade of efferocytosis." (PMID 32487125, 2020). "In this work, we established a direct correlation between DDR1 phosphorylation and tumor cell expression of ICAM1 and VCAM1." (PMID 32090682, 2020). "One study demonstrated that IL6 signaling activated by systemic thermal therapy in a mouse model with the ovalbumin-expressing B16 tumor significantly upregulated E/P-selectin and ICAM1, which enhanced the CD8+ T-cell trafficking." (PMID 33381115, 2020).
tumor (continued). "ICAM-1 is also expressed on the cell surface of many cancer types and facilitates tumor progression and metastasis." (PMID 32370748, 2020). "Six hours after injection, clear induction of ICAM‐1 on tumor vessels was observed, which was even more pronounced 24 h after injection, indicating prolonged endothelial activation." (PMID 31912630, 2020). "On the other hand, it has been reported that LFA-1 and MAC-1 mediate adhesion of PMN to ICAM-1-expressing melanoma cells, allowing tandem migration of tumor cells, and thereby their extravasation." (PMID 32092981, 2020). "In cancer patients with an activity level of 150 or 300 min/week at 50%–70% of maximum heart rate (i.e., moderate-intensity exercise), ICAM-1 levels were lower, which in turn reduced the amount of circulating tumor cells in the vessels." (PMID 31936342, 2020). "We also carefully evaluated the on‐target, off‐tumor sites for ICAM1‐targeting therapeutics in normal tissues." (PMID 33344137, 2020). "The LFA-1/ICAM-1 activates the formation of the immunological synapse via cell–cell interactions between immune effector cells and tumor cells." (PMID 32906721, 2020). "We observed however that, although there were no significant changes in ICAM-1 expression in the irradiated xenografts compared to the mock-treated, overall ICAM-1 levels were lower in the xenograft tumour tissue compared to cell lysates from in vitro models." (PMID 32135474, 2020). "The results of mean fluorescence intensity of in vivo imaging showed that ICAM1-specific CAR-T cells were effective in reducing the tumor sizes in MDA-MB-231 xenograft tumors (p < 0.01)." (PMID 33072116, 2020). "To further determine the mechanism of activated fibroblasts on tumor invasion, we performed qRT-PCR to detect the expression levels of five genes (ICAM-1, VEGF-C, MMP2, MMP3, and MMP9) that were reported to be involved in ESCC invasion." (PMID 32637576, 2020). "VCAM-1 mediates interactions between neutrophils and CTCs in the circulation, while ICAM-1 mediates interaction between arrested neutrophils and CTCs to facilitate tumor cells adhesion to the endothelium." (PMID 33101283, 2020). "The binding of ICAM-1 with αLβ2 and β2 integrin on neutrophils facilitates tumor cell adhesion and extravasation." (PMID 31835465, 2019). "As a transmembrane leukocyte and endothelial cell protein, ICAM-1 enhances tumor cell adherence to endothelial cells." (PMID 31312656, 2019). "In contrast to the positive influence of tumor ICAM-1 expression on T-cell activity, tumor cell PD-L1 and PD-L2 expression reduce T-cell driven anti-tumor cytotoxicity by binding to the PD-1 immune checkpoint receptor expressed on the surface of T-cells." (PMID 31164960, 2019). "The ability of T-cells to increase ICAM-1 expression on neighboring tumor and stromal cells is thought to be mediated primarily through IFN-γ produced by the T-cells." (PMID 31164960, 2019). "Our in vitro data suggests that ICAM-1 modulates tumor cell migration and release of pro-migratory factors to recruit LSECs and HSCs." (PMID 31511625, 2019). "To do so, we injected mice with ICAM-1 siRNA 48 and 24 hours before tumor cell injection and three and six days after." (PMID 31511625, 2019). "The rationale of using pre-treatment is based on our former observation of carbenoxolone to reduce tumor colonization in the lung via the reduction of ICAM1." (PMID 31533288, 2019). "Tumor cells were subjected in vitro to either stimulation with sICAM-1 or blockage of LFA-1 binding capacity to ICAM-1 with anti-CD11a antibody, prior to injecting them intrasplenically to syngenic mice." (PMID 31511625, 2019). "This allows us to address concerns related to CAR T cells recognizing antigens expressed in non-tumor tissues by taking advantage of cross-reactivity between human and murine ICAM-1 by our CAR." (PMID 31337787, 2019). "Adhesion molecules such as ICAM-1 are essential for the adhesion of tumor cells to endothelial cells and thus mediate tumor cell metastasis." (PMID 31766230, 2019).
tumor (continued). "Enhanced PGE2 secretion in the C26 cell/LSECs co-cultures goes along with our previous studies, where we demonstrate that ligation of tumor LFA-1 with endothelial ICAM-1 drives COX-2 mediated LSECs secretion of IL-1β15." (PMID 31511625, 2019). "The interction between tumor and lymphocytes through ICAM-1 plays an important role in leukocyte adhesion, transduction, and cytolysis." (PMID 31297450, 2019). "The subset with low lysablity expressed ICAM-1 at levels 10 fold lower than those of tumor clones with high lysability." (PMID 31297450, 2019). "From a clinical perspective, up-regulation of ICAM-1 in the tumor microenvironment have been shown to be related to favorable prognosis among patients with various cancers, suggesting an enhancement in cancer immunosurveillance." (PMID 31231358, 2019). "The surviving irradiated tumor cells display increased expression of death receptor Fas, intercellular adhesion molecule (ICAM-1) and major histocompatibility complex 1 that allows enhanced recognition by activated T-cells." (PMID 31362708, 2019). "As no standard immunohistochemistry antibody for murine ICAM-1 exists, we first validated the specificity of the antibody (clone 3E2) using subcutaneous tumor tissue of 293T cells expressing mouse ICAM-1." (PMID 31337787, 2019). "Leukocytes express LFA-1, the receptor that binds ICAM-1, and tumor cell expression of ICAM-1 facilitates leukocyte adhesion to tumor cells through ICAM-1/LFA-1 interactions." (PMID 31164960, 2019). "To further analyze the in vivo effect of reduced ICAM-1 expression in the liver in tumor formation, in the next set of experiments we examined metastatic tumor foci formation and growth in mice with silenced expression of LSEC ICAM-1." (PMID 31511625, 2019). "For example, the high expression of VEGF and other growth factors reduces endothelial ICAM-1 and VCAM-1 expressions in tumor tissues, causing the lymphocyte–endothelial interactions to become inefficient." (PMID 31600937, 2019). "Altogether, these results indicate that endothelial ICAM-1/tumor LFA-1 interplay facilitates liver metastasis through the recruitment of a prometastatic stroma composed of activated HSCs and angiogenic LSECs." (PMID 31511625, 2019). "Under both experimental conditions, disrupting endothelial ICAM-1/tumor LFA-1 interaction results in a dramatic reduction in the secretion of IL-1β, IL-6, PGE2 and TNFα into the co-culture supernatant." (PMID 31511625, 2019). "The involvement of ICAM-1 in tumor cell adhesion to the hepatic sinusoidal wall was confirmed by in vivo retention assays." (PMID 31511625, 2019). "ICAM-1 and L-selectin have even been shown to contribute co-operatively to the anti-tumor reaction by regulating tumor lymphocyte infiltration." (PMID 31457007, 2019). "In our experimental model, enhanced secretion of IL-1β, PGE2, TNF-α, and IL-6 occurs following CRC cells/LSECs crosstalk in a tumor LFA-1/LSEC ICAM-1 interaction dependent fashion." (PMID 31511625, 2019). "As predicted, we found that blocking tumor cell ICAM-1 results in decreased T-cell mediated Ewing cell apoptosis compared to control." (PMID 31164960, 2019). "We therefore analyzed the expression of a number of adhesion-associated proteins (E-selectin, N-cadherin, ICAM-1, VCAM-1; CD44, integrin α4, integrin α5, integrin β1) in tumor cells and endothelial cells using Western blot." (PMID 30717801, 2019). "These included ICAM1 (CD54) (intercellular adhesion molecule 1), which mediates adhesion of circulating leukocytes to the blood vessel wall and activated endothelium and contributes to tumor metastasis." (PMID 31661894, 2019). "In an orthotopic xenograft mouse model, overexpression of IL-35 contributed significantly to tumor establishment in an ICAM1-dependent manner." (PMID 31681561, 2019).
tumor (continued). "In concordance with our previous results using ICAM-1 antibodies, adhesion of tumor cells to ICAM-1 silenced LSECs was 2-fold lower than tumor adhesion to LSECs expressing ICAM-1 derived from mice injected with scramble siRNA." (PMID 31511625, 2019). "Tumor foci of ICAM-1 siRNA treated mice contained 55% less αSMA and 45% CD31 expression than control ones." (PMID 31511625, 2019). "The extent to which tumor-induced brain Icam1 expression drives peripheral immune cell trafficking to brain, remain uninvestigated." (PMID 31019214, 2019). "Expression of ICAM-1 on tumor cells negatively correlates with tumor progression and development, including tumor size and lymph node metastasis." (PMID 31297450, 2019). "ICAM-1 expression on tumor cells can also serve as a mechanism by which tumor cells enhance T-cell activation." (PMID 31164960, 2019). "Intercellular adhesion molecule (ICAM-1) helps in the adhesion of MM cells to marrow stromal cells with resultant tumor proliferation." (PMID 31544840, 2019). "Analysis of the results revealed that genetic depletion of Il1b in fibroblasts in the primary tumour led to a significant decrease in the expression of E-Selectin, P-Selectin, ICAM-1 and VCAM-1 and in ECs sorted from primary tumours." (PMID 31558756, 2019). "Focusing on the tumour suppressor miRNA, bta‐miR‐181a and bta‐miR‐181b, we identified putative messenger RNA targets and confirmed the interaction of bta‐miR181a with ICAM‐1." (PMID 30370674, 2019). "As ICAM-1 was identified as a key mediator of CVA21 anti-tumor immunity, we next sought to identify the immune cell component responsible for CVA21 recognition, and downstream immune activation." (PMID 31262361, 2019). "To further elucidate the role for ICAM-1 (on tumor cells or immune effectors) in coordinating CVA21 efficacy, we took advantage of AML patient samples." (PMID 31262361, 2019). "These hosts ICAM-1 mediated tumor/endothelial crosstalk initiates inflammatory and angiogenic responses driving to liver metastasis." (PMID 31511625, 2019). "Here, we demonstrated that SP- and GN-DU145 cells, which exhibited high tumorigenic potential in SCID mice, were able to establish tumor tissue by escaping from NK cell attack due to suppression of ICAM1 expression." (PMID 31619256, 2019). "Further strengthening the role of ICAM-1 in tumor metastasis, tumor cell lines transfected with ICAM-1 showed enhanced invasive capacity and proliferation in vitro and ICAM-1 blockade have been shown to decrease tumor cell invasion in vitro." (PMID 31231358, 2019). "Loss of adhesion molecule ICAM1, gain in TACSTD2 expression, and increased tumor cell–ECM interaction under DAPK1 loss seem to be central events in this process." (PMID 31772156, 2019). "In the present study we aimed to elucidate the role of ICAM-1, produced by LSECs, on the crosstalk between tumor and host cells in early steps of liver metastasis." (PMID 31511625, 2019). "In liver cancer, ICAM-1 promotes tumor formation and metastasis, and its overexpression is correlated with poor prognosis." (PMID 31312656, 2019). "As far as we know, this is the first report on ICAM-1 dependent tumor transmigration through freshly isolated LSECs and HSCs." (PMID 31511625, 2019). "We then treated blocking antibodies against representative activating receptors (NKG2D, NKp30, NKp46 or DNAM-1) and an adhesion molecule (ICAM-1) in NK101/tumor cell co-cultures." (PMID 31126350, 2019). "ICAM-1 has previously been shown to have anti-cancer activity in numerous studies through its recruitment of immune cells to the tumour." (PMID 30791601, 2019). "Altogether, our results point out host endothelial ICAM-1 as a potent inflammatory and angiogenic promoter that mediates the infiltration of tumor cells and stromal cell recruitment into the tumor mass." (PMID 31511625, 2019).
tumor (continued). "Patients with higher secretion of PIGF, TIE-2, ICAM-1 or VCAM-1 from their tumour explants displayed higher nodal status, reflective of a more aggressive cancer phenotype." (PMID 31217905, 2019). "We examined cross-reactivity of CAR T cells toward both human and murine ICAM-1 and ICAM-1 expression in human and mouse tissues to demonstrate that both efficacy and on-target, off-tumor toxicity can be studied in our preclinical model." (PMID 31337787, 2019). "In this analysis, no expression of αXß2 on tumor cells was shown, and therefore, the assumption that tumor cells make use of αXß2 as an alternative ligand for ICAM-1 still needs to be further investigated." (PMID 30657059, 2019). "Attenuation of ICAM-1 by AF1q on tumor cells disadvantages host anti-tumor defenses through the trafficking of lymphocytes, which affects tumor progression and metastasis." (PMID 31297450, 2019). "We have previously shown that activated LSECs release inflammatory factors after ICAM-1 ligation with tumor LFA-1, that correlates with a decreased lymphocyte cytotoxic activity." (PMID 31511625, 2019). "To further confirm these findings in vivo, we silenced LSEC ICAM-1 by siRNAs injection and then checked for in vitro adhesion and transmigration of tumor cells to LSECs isolated from those mice (See silencing efficiency in Suppl." (PMID 31511625, 2019). "At this time point, ICAM-1-silenced livers contain 50% fewer tumor cells than livers from mice injected with scramble siRNA." (PMID 31511625, 2019). "On the other hand, the mRNA expression levels of A20 and ICAM‐1 were enhanced in many cancer tumor samples, and especially, enhancement of A20 expression was observed in all tumor samples." (PMID 31580526, 2019). "In this model, treatment with heparin reduced ICAM-1 expression and tumour invasion/adhesion both in vitro and in vivo." (PMID 29772648, 2018). "ICAM-1 is then able to trigger migration-related signaling pathways inside tumor cells, thus promoting extravasation and colonization of adjacent tissues." (PMID 30200242, 2018). "In conclusion, we showed that pre-culturing CD8+ T-cells on substrate-immobilized CCL21 + ICAM1 increases both the proliferation of T-cells and their tumor-killing capacity, leading to enhanced tumor suppression abilities." (PMID 29942308, 2018). "When ICAM-1 expression in cancer cells was knocked down by shRNA, tumor growth and invasion were significantly suppressed and mice implanted with these cells exhibited improved survival." (PMID 29670046, 2018). "The archazolid-induced adhesion of tumor cells was independent from the endothelial cell adhesion molecules ICAM-1, VCAM-1, E-selectin and N-cadherin, as their expression was not regulated by the compound." (PMID 30204757, 2018). "In this study, we explored the role played by the LFA-1 ligand ICAM-1 in T cell retention in the tumor milieu." (PMID 30258446, 2018). "Among the positive cases of ICAM1 in tumor cells, the expression was predominantly detected in the invasive front of the tumor, whereas around one third showed prominent staining in the central tumor areas." (PMID 30082828, 2018). "A series of lines of evidences suggests that ICAM1 can potentially be involved in invasion of tumor cells and metastasis of human breast cancer." (PMID 30082828, 2018). "In our view, transient treatment with ICAM-1 blocking antibodies together with immunotherapy would release cytotoxic T lymphocytes caught up in clusters, setting them free to kill tumor cells or egress to the dLNs and to subsequent lesions." (PMID 30258446, 2018). "Our final finding suggested that invasive tumor cells induced perforin downregulation within SN by ICAM-1 and TGFβ2 signaling." (PMID 29966014, 2018). "We then postulated that the incremented CD8+ T cell retention was due to ICAM-1 mediated lymphocyte-tumor interaction." (PMID 30258446, 2018). "Tumor infiltrating lymphocytes stained always positively for ICAM1, both in the center of the tumor and the periphery." (PMID 30082828, 2018).